MAMDC2 (MAM domain containing 2)
Synonyms: MGC21981
Tractability: Antibody: UniProt places it where antibodies can reach, with medium confidence; UniProt predicts a signal peptide or a membrane-spanning region; its Gene Ontology location is reachable by antibodies, with medium confidence; the Human Protein Atlas places it where antibodies can reach. PROTAC: ubiquitination databases record sites on it.
Gene: Protein-coding gene on chromosome 9 (70,043,820 to 70,226,987, forward strand). Ensembl gene ENSG00000165072.
Subcellular location: Secreted, extracellular space, extracellular matrix
Subcellular location (Human Protein Atlas): Nuclear speckles; Plasma membrane; Predicted to be secreted
Gene Ontology:
Molecular function: protein binding
Cellular component: endoplasmic reticulum; membrane
Genetic constraint (gnomAD): Loss-of-function variants: 52 observed, 76.46 expected, observed/expected ratio (o/e) 0.68, 90% interval 0.54 to 0.86. The upper end of that interval is the gene's LOEUF score, 0.86, which puts it in group 3 of 6, group 1 being the genes least tolerant of losing a copy. Missense variants: 727 observed, 758.87 expected, observed/expected ratio (o/e) 0.96, 90% interval 0.9 to 1.02. Synonymous variants: 291 observed, 277.39 expected, observed/expected ratio (o/e) 1.05, 90% interval 0.95 to 1.16.
Homologues: Orthologues: chimpanzee MAMDC2 (99% identical), macaque MAMDC2 (99% identical), rabbit MAMDC2 (92% identical), dog MAMDC2 (92% identical), pig MAMDC2 (91% identical), mouse Mamdc2 (90% identical), guinea pig MAMDC2 (90% identical), rat Mamdc2 (90% identical), tropical clawed frog mamdc2 (65% identical), zebrafish mamdc2a (54% identical). Paralogues in human: MAMDC4 (26% identical), MALRD1 (24% identical), MDGA2 (20% identical), MDGA1 (16% identical).
Diseases named in the same sentence as MAMDC2 in open-access papers:
MAMDC2 is named in the same sentence as 24 diseases in open-access papers, as found by Europe PMC text mining. Sharing a sentence is not in itself a finding about the gene and the disease. The quoted sentences say what the papers report.
breast carcinoma (6 papers, 2020 to 2025). "Many genes such as ABCA8, MFAP4 and MAMDC2 also been potential diagnostic and prognostic biomarkers in hepatocellular carcinoma, breast cancer and ovarian cancer." (PMID 37563710, 2023). "The KM plotter analysis revealed that MAMDC2 expression level is closely associated with the survival rates of the breast cancer patients in the ER+ group, which was completely abrogated in the triple‐negative subtype." (PMID 32707597, 2020). "Instead, we used the Kaplan‐Meier (KM) plotter database and found a close relation between the MAMDC2 expression level and survival rates of the breast cancer patients." (PMID 32707597, 2020). "A gene expression analysis reported MAMDC2 as one of three genes that are correlated with disease‐free survival of breast cancer patients." (PMID 32707597, 2020). "A study reported that MAMDC2 exhibited tumor-suppressive activity and may constitute a biomarker for breast cancer treatment." (PMID 38886662, 2024). "We also found that ER may suppress MAMDC2 expression, suggesting this protein as an important growth regulator in ER+ breast cancer cells." (PMID 32707597, 2020). "MAMDC2 is significantly correlated with disease-free survival of breast cancer patients." (PMID 32854705, 2020). "Overall, these clinical data may indicate that MAMDC2 is a reliable prognostic biomarker for breast cancer." (PMID 32707597, 2020). "We report that MAMDC2 has a tumour‐suppressive role and, as a secretory protein, it might be useful as a biomarker for breast cancer treatment." (PMID 32707597, 2020). "Several studies reported that MAMDC2 gene expression is differentially regulated in certain human cancer types, including CML, head and neck squamous cell carcinoma and breast cancer." (PMID 32707597, 2020).
gastric cancer (2 papers, 2017 to 2022). A primary or metastatic malignant neoplasm involving the stomach. "MDGA2/MAMDC1 acts as an antitumor molecule in gastric cancer 45; however, the role of MAMDC2 in cancer, if any, has yet to be elucidated." (PMID 29030909, 2017).
head and neck squamous cell carcinoma (2 papers, 2020 to 2023). A squamous cell carcinoma that arises from any of the following anatomic sites: lip and oral cavity, nasal cavity, paranasal sinuses, pharynx, larynx, and salivary glands. "MAMDC2 was differentially expressed between normal tissues and several solid tumors, including BC, head and neck squamous cell carcinoma, and GC." (PMID 37404760, 2023). "MAMDC2 is known as a target of miR-196a in head and neck squamous cell carcinoma." (PMID 32854705, 2020).
invasive ductal breast carcinoma (2 papers, 2019 to 2022). The most common type of invasive breast carcinoma, accounting for approximately 70% of breast carcinomas. "Some studies have also shown that MAMDC2 plays a key role in the development of invasive ductal carcinoma of the breast." (PMID 35600357, 2022).
lung carcinoma (2 papers, 2016 to 2022). "Of 30 top ranked genes, FAM107A, MAMDC2, SOX17, TCF21, PTPRH, and CDO1 have been previously reported with aberrant DNA methylation in lung cancer." (PMID 27610367, 2016).
Achalasia (1 paper, 2022). A disorder of esophageal motility characterized by the inability of the lower esophageal sphincter to relax during swallowing and by inadequate or lacking peristalsis in the lower half of the body of the esophagus. "Finally, we observed a significant decrease in MAMDC2 in the proximal esophageal mucosa of achalasia patients compared to controls, but this change was not significant in the distal esophagus." (PMID 36450816, 2022).
atherosclerosis (1 paper, 2018). A disease characterized by the build-up of fatty material and calcium deposition in the arterial wall resulting in partial or complete occlusion of the arterial lumen. "Among novel factors in atherosclerosis, we identified matrilin-2, the collagen IV crosslinking enzyme peroxidasin as well as the poorly characterized MAM-domain containing 2 (Mamdc2) protein as being up-regulated in the ECM during atherogenesis." (PMID 29208753, 2018).
breast tumour (1 paper, 2020). "The expression level of MAMDC2 was down‐regulated ~5.9‐fold in the breast tumour tissues compared with paired normal tissues." (PMID 32707597, 2020). "To discover new potential biomarkers, we analyzed the gene expression profiles of breast tumor tissues and identified MAMDC2 as a down‐regulated gene." (PMID 32707597, 2020). "Furthermore, when we analysed, the MAMDC2 expression using two GEO profiles, that in aggressive breast tumour subtypes, was relatively higher than non‐aggressive or less aggressive subtypes." (PMID 32707597, 2020). "To compare the MAMDC2 expression in different breast tumour cell lines, we performed RT‐PCR." (PMID 32707597, 2020).
cervical cancer (1 paper, 2025). A primary or metastatic malignant neoplasm involving the cervix. "Pan-cancer analysis shows that MAMDC2 is significantly downregulated in 15 malignancies, including urothelial carcinoma, invasive breast cancer, cervical cancer, and endometrial cancer." (PMID 40427044, 2025).
colorectal cancer (1 paper, 2025). A primary or metastatic malignant neoplasm that affects the colon or rectum. "First, we preliminarily explored the expression characteristics of MAMDC2 in colorectal cancer and its potential association with the EMT process and MYLK expression in CAFs through bioinformatics analysis and in vitro experiments." (PMID 40427044, 2025). "Our findings identify MAMDC2 as a stromal-associated effector of EMT–stromal crosstalk in MSS colorectal cancer with a high TSR, demonstrating its high expression in tumors with a high TSR and peritoneal metastases." (PMID 40427044, 2025). "In this study, we systematically analyzed the expression characteristics of MAM domain-containing genes in CRC and investigated the potential functional roles of MAMDC2 in MSS colorectal cancer with a high tumor stroma ratio (TSR)." (PMID 40427044, 2025). "IHC confirmed MAMDC2 overexpression in MSS colorectal cancer with a high tumor stroma ratio (TSR) and peritoneal metastatic lesions (p < 0.01)." (PMID 40427044, 2025). "In conclusion, our study is the first to systematically elucidate the expression patterns and functional roles of MAMDC2 in CRC, particularly in MSS colorectal cancer with a high TSR." (PMID 40427044, 2025). "Second, we only verified that MAMDC2 can be secreted by colorectal cancer cells but did not analyze its expression and secretion in CAFs, which is critical to clarify its mode of action in tumor stroma crosstalk." (PMID 40427044, 2025). "However, the specific biological function of MAMDC2 in colorectal cancer remains unclear, and there is currently a lack of in vivo experimental verification." (PMID 40427044, 2025).
fatty liver disease (1 paper, 2024). A reversible condition wherein large vacuoles of triglyceride fat accumulate in liver cells via the process of steatosis. "Among downregulated genes (KIT, NTRK2, MAMDC2, and ANXA13), KIT could regulate apoptosis, NTRK2 was revealed that capable of activating apoptosis pathways with Brain derived neurotrophic factor (BDNF), which may promote the progression of fatty liver disease." (PMID 38665091, 2024).
Kabuki syndrome (1 paper, 2017). Kabuki syndrome (KS) is a multiple congenital anomaly syndrome characterized by typical facial features, skeletal anomalies, mild to moderate intellectual disability and postnatal growth deficiency. "Interestingly, MAMDC2 gene is mutated in patients with Kabuki syndrome, a multiple congenital anomaly/mental retardation syndrome characterized by a distinct facial appearance." (PMID 29030909, 2017).
lipid metabolism disorders (1 paper, 2024). "However, the functions of MAMDC2 and ANXA13 in lipid metabolism disorders are still unclear." (PMID 38665091, 2024).
neuroblastoma (1 paper, 2017). Neuroblastoma (NB) is the most common solid, extracranial childhood tumor. "SNPs rs10509225 and rs341295 too are associated to cholesterol, lipoproteins and disease state, while association to stroke and neuroblastoma was shown by two SNPs related respectively to WDR2 and MAMDC2 genes." (PMID 28287094, 2017).
tumor (13 papers, 2016 to 2025). "Low expression of MAM domain containing 2 encoded by MAMDC2, has been associated with tumour necrosis and invasion, while an over-expression of DIX domain containing 1 regulated by DIXDC1, has been shown to have a positive effect of suppressing cancer cell migration and invasion." (PMID 27341628, 2016). "In cancer, MAMDC2 has been definitively identified as a potential tumor suppressor in ER+ breast tumors, where its downregulation promotes tumor progression by attenuating MAPK signaling." (PMID 40427044, 2025). "Through bioinformatic analysis, we identified four MAM domain-containing genes (EGFL6, MEP1A, MEP1B, and MAMDC2) that showed significant differential expression between tumor and adjacent normal tissues in CRC." (PMID 40427044, 2025). "Recently, two other genes (CLIC5 and MAMDC2) have also been reported to function as tumor suppressors in some cancers." (PMID 40535574, 2025). "There were contradictory reports on the involvement of MAMDC2 in tumor progression in the literature." (PMID 37404760, 2023). "Six diagnostic genes were mutated in descending frequency in the tumor group: COL4A1, ABCA8, MAMDC2, FAP, TMEM100, and LY6E." (PMID 36685898, 2022). "MAMDC2 is a known tumor suppressor involved in glycosaminoglycan binding, whereas NPIPB6 has not previously been associated with cancers to the best of our knowledge." (PMID 34149812, 2021). "The average tumour weight of MAMDC2‐expressing xenografts was ~62% of controls (P < .05), indicating that the MAMDC2 expression can attenuate in vivo tumour cell proliferation." (PMID 32707597, 2020). "Collectively, we report that MAMDC2 is a novel tumour inhibitor gene that can be used a prognostic marker for the ER‐positive breast tumour." (PMID 32707597, 2020). "Our findings provide insights into the tumor stroma crosstalk mediated by MAMDC2 and may offer potential therapeutic targets for CMS4 CRC." (PMID 40427044, 2025). "Based on these results, we speculate that MAMDC2, as a secreted protein, may be released from tumor cells into the tumor microenvironment, where it regulates MYLK expression in CAFs." (PMID 40427044, 2025). "Our findings suggest that the MAMDC2/MYLK axis may play an important role in tumor stroma interactions and the progression of high-stromal CRC." (PMID 40427044, 2025). "MAMDC2 may exert its tumor suppressive role by attenuating the MAPK signaling pathway as an extracellular regulator." (PMID 32707597, 2020). "Furthermore, MAMDC2 expression reduced in vivo growth of T‐47D xenograft tumours." (PMID 32707597, 2020). "A recent publication based on the application of multivariate regression algorithms suitable for higher dimension data identified 3 genes (MAMDC2, SYNPO2 and ARMH4) as biomarkers of gene expression signatures for tumor and marginal tissue zones." (PMID 38188288, 2023). "COL4A1, COL6A3, FAP, and LY6E were up-regulated in the tumor group in the training set, whereas ABCA8, MAMDC2, TMEM100, and TMEM266 were down-regulated." (PMID 36685898, 2022). "For instance, the tumor microenvironment in CMS4 CRC is characterized by abundant desmoplastic stroma and activated CAFs, which may alter the functional output of MAMDC2 through paracrine signaling or microenvironmental remodeling." (PMID 40427044, 2025). "Intriguingly, this tumor-suppressive function appears to be context-dependent, as MAMDC2 exhibits no significant regulatory effects in the more aggressive triple-negative breast cancer." (PMID 40427044, 2025). "Although the mean body weight of each group did not change significantly, the Tet‐On‐MAMDC2 xenograft mice exhibited tumour regression." (PMID 32707597, 2020). "In addition, we have not elucidated the precise pathway of tumor-derived MAMDC2 entry into CAFs, the molecular mechanism by which MAMDC2 regulates MYLK expression in CAFs, or its biological effects on CAFs—key questions that require further investigation." (PMID 40427044, 2025).
tumor (continued). "Notably, MAMDC2 is significantly enriched in highly stromal peritoneal metastatic tissues, with its expression levels positively correlating with tumor stromal abundance, likely induced by the tumor stromal microenvironment and driving CRC progression through tumor stroma interactions." (PMID 40427044, 2025).
cancer (11 papers, 2016 to 2025). A tumor composed of atypical neoplastic, often pleomorphic cells that invade other tissues. "Importantly, we identified that cancer cell-derived MAMDC2 promotes MYLK expression in cancer-associated fibroblasts (CAFs) through paracrine signaling." (PMID 40427044, 2025). "The results indicated that seven risk genes (SERPINE1, LAMC2, MYLK, IL21R, KRT81, MAMDC2, and PAEP) of the signature were differentially expressed in the cancer tissues compared to the normal tissues." (PMID 37636564, 2023). "Although previous reports have shown that the MAMDC2 expression is associated with various human cancer types, its exact molecular function has not been defined." (PMID 32707597, 2020). "Furthermore, gene expression regulation and downstream signaling pathways of MAMDC2 could differ between these cancers." (PMID 40427044, 2025). "The results showed that TPX2 and BIRC5 were upregulated, while AGER, TEK, CLIC5, MAMDC2, EMCN, and SEMA3G were mostly downregulated in multiple cancer types." (PMID 40535574, 2025). "Besides, several genes (including MAMDC2, F2RL2, and KCNMA1) were enrolled as biomarker for the prognosis of varying cancers." (PMID 37313409, 2023). "Because we could not detect endogenous MAMDC2 protein in most cancer cell lines, we performed the experiment using Tet‐On‐MAMDC2 cells." (PMID 32707597, 2020).
MAMDC2 also shares sentences with these, for which no sentence is quoted: endometrial cancer (1 paper); hepatocellular carcinoma (1); invasive breast carcinoma (1); mesothelioma (1); ovarian carcinoma (1); Stroke (1); thyroid tumours (1); urothelial carcinoma (1).